EGFR (epidermal growth factor receptor)
Diseases named in the same sentence as EGFR in open-access papers (continued):
Sharing a sentence is not in itself a finding about the gene and the disease.
lung cancer (continued). "Although TLS is associated with favorable prognosis, the recurrence is more frequently observed in EGFR mutated lung cancer, the eventual offset of this consequence occurs, as for patients with EGFR mutation, the survival curves of TLS + and TLS- overlap." (PMID 38528507, 2024). "Osimertinib, one of the third-generation EGFR-tyrosine kinase inhibitors (TKIs) designed to target EGFR T790M mutation, significantly improves the prognosis of lung cancer." (PMID 39497720, 2024). "LCA46 was generated from the biopsy of a lung cancer patient who carried the EGFR mutation before neoadjuvant therapy." (PMID 38643164, 2024). "In a more recent study using xenograft mice, EGFR-mutated lung cancer cells were observed to produce ET1 when treated with EGFR inhibitors." (PMID 38785410, 2024). "Initially, mutations in the epidermal growth factor receptor (EGFR) gene were identified as the driver of lung cancer." (PMID 39590127, 2024). "Simultaneous use of antituberculosis drugs and TKIs in a comorbidities patient for EGFR-mutated lung cancer patients with active TB has shown a safe and alternative treatment strategy." (PMID 38298194, 2024). "The CHRYSALIS trial demonstrated that amivantamab was effective in reducing tumor size and improving survival in patients with lung cancer with EGFR Ex20Ins mutation." (PMID 38910714, 2024). "Oncogene-driven LUAD, such as lung cancer harboring activating epidermal growth factor receptor (EGFR) mutations, is known to be fairly resistant to ICI therapy, which can be at least partially explained by the adenosine pathway." (PMID 39335114, 2024). "In the multivariate analysis of PFS, the baseline PDC response was independently associated with a better PFS in untreated patients with EGFR/ALK-positive lung cancer (hazard ratio: 0.20, 95% CI: 0.07–0.0.60, p = 0.004)." (PMID 38398169, 2024). "In this single‐center, retrospective study, we evaluated patients with non‐small cell lung cancer harboring an epidermal growth factor receptor mutation who were initiated on 40 mg osimertinib every other day." (PMID 38279684, 2024). "We analyzed patients with unresectable stage III/IV or recurrent NSCLC harboring EGFR mutations using a prospective umbrella-type lung cancer registry (CS-Lung-003)." (PMID 38347279, 2024). "This study underscores the importance of EGFR mutation detection in stage IV lung cancer patients and supports the need for personalised therapeutic approaches to improve outcomes in this patient population." (PMID 39421175, 2024). "A possible explanation is that response to chemotherapy is enhanced by IGF-IR targeting only in a subset of tumors, following the well-known precedent that adding EGFR inhibitors to chemotherapy in lung cancer is only helpful in tumors with EGFR mutations." (PMID 39362991, 2024). "In patients with epidermal growth factor receptor (EGFR) mutation-positive lung cancer, EGFR tyrosine kinase inhibitors (TKIs) are considered the standard first-line treatment." (PMID 38539522, 2024). "A recent study revealed that lung cancer in the Asian population is dominated by epidermal growth factor receptor (EGFR) variants, mainly for non-small cell lung carcinoma (NSCLC)." (PMID 38245692, 2024). "Gefitinib, the orally administered tyrosine kinase inhibitor for lung cancer patients harboring the epidermal growth factor receptor (EGFR) mutations across therapy lines." (PMID 39119602, 2024). "In previous studies, there were no related clinical characteristics that predicted the future occurrence of BM after resection of lung cancer in patients with EGFR mutations." (PMID 38464823, 2024). "In Taiwan, epidermal growth factor receptor (EGFR) mutations are the most common disease-associated mutations in lung cancer with an incidence rate around 55%, and several EGFR tyrosine kinase inhibitors (EGFR-TKIs) are used as first-line therapy." (PMID 38687753, 2024).
lung cancer (continued). "Preclinical studies have shown that poziotinib exhibits potent activity against various EGFR mutations, resulting in tumor regression in lung cancer models." (PMID 38611728, 2024). "Osimertinib is effective for treating patients with lung cancers with sensitive epidermal growth factor receptor (EGFR) mutations." (PMID 39139611, 2024). "Osimertinib is a first‐line or adjuvant therapy for non‐small cell lung cancer (NSCLC) harboring an epidermal growth factor receptor (EGFR) mutation." (PMID 38279684, 2024). "According to the TCGA database, 9% of lung cancer patients harbor EGFR mutations, while 2% exhibit ERBB2 mutations." (PMID 39596025, 2024). "The latest version of the National Comprehensive Cancer Network guidelines in 2023 recommends osimertinib as the first choice for systemic treatment in patients with non–small cell lung cancer (NSCLC) harboring an EGFR L858R mutation." (PMID 38204337, 2024). "Among the treatments available in a precision medicine landscape, osimertinib has emerged as a promising drug for managing epidermal growth factor receptor (EGFR)-mutated lung cancer." (PMID 39108772, 2024). "EGFR overexpression is a common feature of lung cancer and is associated with poor patient survival." (PMID 39453005, 2024). "Few reports showed a difference in the treatment efficacy of osimertinib depending on the VAF of the T790M mutation in a re-biopsy after treatment for EGFR-mutant lung cancer." (PMID 39519246, 2024). "Just like EGFR mutations in specific lung cancers, or BRAF mutations in melanoma and certain thyroid cancers, several novel prognostic biomarkers for HNSCC have been identified through recent advancements." (PMID 39199313, 2024). "The global frequencies of these classical EGFR mutations in lung cancer and NSCLC patients were reported as 17% and 33%, respectively." (PMID 38982031, 2024). "Clinical trials on the mutant KRAS-targeted long peptide vaccine for high-risk pancreatic cancer recipients and EGFR-targeted vaccine for high-risk lung cancer recipients are currently underway (NCT05013216, NCT04298606)." (PMID 38890350, 2024). "We established spheroids and organoids by culturing lung cancer cells with EGFR mutation, MSCs and HUVECs on matrigel." (PMID 39766891, 2024). "In this study, we evaluated IL-15 stimulated natural killer cell-derived EVs (NK-EVs) as therapeutic agents in vitro and in vivo in Osimertinib-resistant lung cancer (H1975R) with EGFR mutations (L858R) in combination with carboplatin (CBP)." (PMID 38258094, 2024). "Implying a possible link between the frequency of somatic mutations in EGFR in lung cancer and the genetic ancestry of populations, these findings underscore the need for deeper investigation." (PMID 38581481, 2024). "Targeted therapies for EGFR gene mutations in lung cancers represent one of the most significant and well-studied innovations in the fight against NSCLC, including TKIs and monoclonal antibodies." (PMID 39199653, 2024). "Such as BRAF or KRAS mutations in EGFR‐TKI‐treated lung cancer, or MEK mutations in BRAF inhibitor resistant malignant melanoma." (PMID 39184861, 2024). "Using this updated CTC detection method, we conducted a pilot study to detect EGFR mutations in lung cancer using digital PCR in 12 patients." (PMID 39335743, 2024). "EGFR-targeted therapy based on EGFR TKI has demonstrated unprecedented results on the survival of non–small-cell lung cancer (NSCLC) patients with activating EGFR mutations." (PMID 39353739, 2024). "The overexpression, mutation, or amplification of the EGFR gene increases EGFR activity and contributes to many human cancers, including lung cancers, especially NSCLC." (PMID 39456995, 2024). "EGFR is a significant causal factor in lung cancer development, and its inhibitors have proved effective in treating lung cancer." (PMID 39239557, 2024). "A relevant study explored the treatment strategies for EGFR mutation-positive lung cancer brain metastases." (PMID 38434971, 2024).
lung cancer (continued). "A large cohort of 5363 Chinese lung cancer patients was subjected to genotyping for the detection of EGFR mutations, in which the frequency of the common/typical mutations appeared to be about one-third (34%) compared to ucEGFRmuts (12%)." (PMID 38611009, 2024). "EGFR signaling is associated with diverse functions in lung cancer cells, including increased radioresistance, metastatic capabilities, DNA synthesis, proliferation, and cell cycle arrest." (PMID 38240876, 2024). "Lung cancer EVs contain several tumor-associated proteins, such as EGFR, KRAS, inducer of extracellular matrix metalloproteinase, claudins, and RAB family proteins." (PMID 38893088, 2024). "All non–small-cell lung cancers (NSCLCs) with epidermal growth factor receptor (EGFR) or anaplastic lymphoma kinase (ALK) mutations who received TKIs between 2015 and 2019 in Qatar were included." (PMID 39416762, 2024). "Our study's findings further revealed significant associations between age group and EGFR-positive lung cancer, with individuals aged <50 years having a lower risk compared to those >50 years." (PMID 39429333, 2024). "In non‐small cell lung cancer (NSCLC), epidermal growth factor receptor‐tyrosine kinase inhibitors (EGFR‐TKIs) have been effective in treating EGFR‐mutated lung cancer." (PMID 38379420, 2024). "Currently, EGFR-tyrosine kinase inhibitors (TKIs), such as gefitinib and osimertinib, are the mainstay of first-line therapy for advanced lung cancer with EGFR mutations." (PMID 39343971, 2024). "Considering the targeted therapies for driven mutations, TKIs are highly used in lung cancer, especially for EGFR mutations, namely deletions in exon 19 or point mutations in exon 21 (L858R)." (PMID 38793028, 2024). "Currently, there are FDA-approved targeted therapies for lung cancers with mutations and genomic alterations in EGFR, ALK, ROS-1, NTRK, MET, RET, HER2, and BRAF." (PMID 39272844, 2024). "Several EGFR tyrosine kinase inhibitors (EGFR-TKIs) are effective against EGFR-mutated lung cancer, among which third-generation osimertinib is widely used." (PMID 38466521, 2024). "Overall, EGFR-mutated NSCLC is less responsive to immune checkpoint blockade than classic smoking-associated lung cancer." (PMID 39318388, 2024). "This case report describes a patient with advanced oligometastatic non–small cell lung cancer with EGFR mutations who achieved downstaging through sequential EGFR-TKI-based precision medicine allowing resection of residual disease." (PMID 38204337, 2024). "Epidermal growth factor receptor (EGFR) is an important target for lung cancer therapy because EGFR mutations are frequently observed in lung cancer." (PMID 38338342, 2024). "The NEOS study updated the results of osimertinib as neoadjuvant therapy in patients with EGFR-mutated resectable stage II–IIIB lung adenocarcinoma in the 2022 European Lung Cancer Congress." (PMID 38414743, 2024). "The discovery of tyrosine kinase inhibitors (TKIs) designed to target EGFR mutations in lung cancer patients marked the inception of the precision medicine era in lung cancer." (PMID 38474400, 2024). "scRNA-seq of EGFR-mutated lung cancer patient samples also reveals high BCL2L1 expression, specifically in tumor cells, while MCL1 expression is lower in tumors compared to non-tumor cells." (PMID 39122703, 2024). "These hotspots EGFR mutations observed in our early‐stage lung cancer cohort were consistent with those found in late‐stage lung cancers in another Chinese lung cancer cohort." (PMID 39036344, 2024). "The prognostic role of EGFR mutation status in patients with lung cancer was investigated as early as 2004 to 2005." (PMID 38250731, 2024). "In lung cancer, the major histologic type associated with an EGFR or ALK mutation is adenocarcinoma." (PMID 38398169, 2024). "Second generation EGFR TKIs have demonstrated some success in patients presenting with lung cancers with uncommon EGFR kinase domain mutations." (PMID 38548752, 2024).
lung cancer (continued). "EGFR–tyrosine kinase inhibitors (EGFR-TKIs) are used as the standard treatment for patients with advanced EGFR mutation-driven lung cancer." (PMID 38555474, 2024). "We identify variants that can be targeted with alternative inhibitors to overcome resistance and functionally validate an epidermal growth factor receptor (EGFR) variant that sensitizes lung cancer cells to EGFR inhibitors." (PMID 39424923, 2024). "Currently the standard of care for lung cancer patients presenting with EGFR extracellular domain variants is chemotherapy." (PMID 38548752, 2024). "In lung cancer cells harboring EGFR-sensitive mutations, YAP activation leads to the upregulation and activation of the tyrosine kinase receptor AXL." (PMID 38499647, 2024). "Studies have foundthat lung cancer with EGFR mutations has a lower rate of lymph nodemetastasis and better prognosis than EGFR mutation-negative lungcancer." (PMID 38206165, 2024). "Compound mutations, usually containing common and rare mutations, are found in 2%–25 % of EGFR mutation-positive lung cancers." (PMID 39166093, 2024). "This reliance of tumours upon ERBB signalling is also observed in lung cancer with particularly high prevalence of ERBB1 (EGFR) mutations." (PMID 38434478, 2024). "Ahn utilised radiomics features to identify EGFR mutations in the treatment of primary lung cancer and brain metastases, achieving a prediction AUC of 86.81." (PMID 38773634, 2024). "This work expands our understanding of oncogenesis-induced DNA replication processes and provides a foundation for improved treatments for EGFR-mutated lung cancer by simultaneously targeting HSP70." (PMID 39470734, 2024). "Examples include erlotinib, which was Food and Drug Administration (FDA) approved for use in lung cancer with Epidermal Growth Factor Receptor (EGFR) mutations." (PMID 39659799, 2024). "Genetic testing for specific mutations, such as the BRAF V600E mutation in melanoma or EGFR mutations in lung cancer, helps identify targeted therapies that selectively inhibit cancer cell growth and improve patient outcomes." (PMID 38785712, 2024). "Epidermal growth factor receptor (EGFR) tyrosine kinase inhibitor (TKI) is crucial for patients with lung cancer harboring EGFR mutations." (PMID 38323355, 2024). "With the development of molecular biology and gene diagnosis, it has been found that there are mutations in EGFR in most patients with lung cancer, so basic medical and clinical studies have been carried out to target EGFR mutations." (PMID 39264588, 2024). "Despite these challenges, osimertinib emerges as a promising and well-tolerated treatment option for patients with EGFR mutations in early-stage lung cancer." (PMID 39624538, 2024). "A low prevalence of EGFR mutations has been previously reported in patients with lung cancer with usual interstitial pneumonia (UIP)." (PMID 38783331, 2024). "On the other hand, lung cancer remains one of the most lethal cancers in both men and women, and H1975R cells (resistant to Osimertinib with EGFR T790M and L858R mutations) were chosen." (PMID 39204415, 2024). "The inhibition of EGFR‐TKD hints at its potential to target critical signalling pathways implicated in lung cancer progression." (PMID 38685671, 2024). "For instance, hsa-miR-4787-5p and hsa-miR-3665 have been implicated in resistance against epidermal growth factor receptor inhibitors, a common therapeutic approach in nonsmall cell lung cancer." (PMID 39495117, 2024). "Epidermal growth factor receptor (EGFR) is a significant driver gene in lung cancer, and EGFR mutation frequency is considerably lower in lung squamous carcinoma in comparison to lung adenocarcinoma." (PMID 38769831, 2024). "Recently, the prognosis of lung cancer has been dependent on the presence of EGFR mutations and ALK fusion protein." (PMID 38751406, 2024).
lung cancer (continued). "The advent of targeted therapy with tyrosine kinase inhibitors (TKIs) directed against the epidermal growth factor receptor (EGFR) has led to dramatic improvements of response and progression-free survival (PFS) in patients with EGFR-mutated lung cancer." (PMID 39456595, 2024). "Two patients with lung cancer harboring EGFR‐L858R mutations in exon 21 were treated by surgical resection during successful osimertinib treatment." (PMID 38323355, 2024). "This study This case underscores the importance of detecting germline mutations in the EGFR gene before treatment in lung cancer patients." (PMID 39160638, 2024). "Krug utilizes the changes in exoRNA from the peripheral exosomes to diagnose nonsmall-cell-lung-cancer with a sensitivity of 98% using epidermal growth factor receptor (EGFR) mutations." (PMID 39886659, 2024). "Our results showed that selected patients with lung cancer brain metastases and EGFR mutations or ALK translocations derived clinical benefit from Atezolizumab, Bevacizumab, Carboplatin, and Paclitaxel treatment despite high toxicity rates." (PMID 38610927, 2024). "This drug has been used as a standard first-line treatment for patients with lung cancer harboring EGFR exon 19 deletion or exon 21 L858R mutations from multiple randomized clinical trials." (PMID 38398169, 2024). "For example, lung cancer patients with EGFR mutations can benefit from treatment with EGFR inhibitors, which can inhibit tumor recurrence and invasion." (PMID 39114311, 2024). "For example, EGFR is the most common oncogenic driver gene in non–small cell lung cancer (NSCLC), where exon 19 deletion mutation (19-del) and exon 21 L858R account for 90%5,6." (PMID 38806596, 2024). "Epidermal growth factor receptor (EGFR) mutations are the most important driver mutations in lung cancer." (PMID 38758372, 2024). "In this work, HiCASE focuses on testing a series of EGFR mutations to provide enhanced detection technology for non–small cell lung cancer (NSCLC), enabling a detection sensitivity of 0.01% with 40 ng cell free DNA standard." (PMID 38806596, 2024). "Osimertinib is approved as a standard treatment for non‐small cell lung cancer (NSCLC) patients with epidermal growth factor receptor (EGFR) mutation by FDA." (PMID 39406371, 2024). "SALL4 expression is upregulated in EGFR-mutated lung cancer cells, which promoting lung cancer cells from invading and metastasizing." (PMID 38355684, 2024). "Patients who have non‐small cell lung cancer (NSCLC) with epidermal growth factor receptor (EGFR) mutations are more prone to brain metastasis (BM) and poor prognosis." (PMID 38696655, 2024). "EGFR kinase domain duplication (EGFR-KDD) represents a rare form of EGFR mutation, with an incidence of 0.24% in EGFR mutation of lung cancer." (PMID 38974236, 2024). "These cells, which can be referred to as the DTP cells, were obtained by treating EGFR-mutated lung cancer cells with erlotinib." (PMID 39138145, 2024). "It is also reported that inhibition of both BCL-XL and MCL1 in cell culture models promotes extensive apoptosis in EGFR-mutated lung cancer cells that display an EMT phenotype." (PMID 39122703, 2024). "Computed tomography (CT) features and certain CT-based radiomic features of lung cancer have recently been revealed to be related to EGFR mutation status." (PMID 38679659, 2024). "Nevertheless, there is a scarcity of studies that have concurrently examined EGFR mutations and ILAs in the assessment of prognosis among patients with lung cancer, particularly those in advanced stages." (PMID 38783331, 2024). "Further research has revealed that its loss causes dysregulation of MDM2 expression through the EGFR signaling pathway, contributing to lung cancer development." (PMID 38634049, 2024). "For example, females are at an increased risk compared to males of developing lung cancer with a driver mutation, such as the epidermal growth factor receptor (EGFR)." (PMID 38388856, 2024).